CDK1 (cyclin dependent kinase 1)
Diseases named in the same sentence as CDK1 in open-access papers (continued):
Sharing a sentence is not in itself a finding about the gene and the disease.
ZIKV infection (1 paper, 2022). "We propose that the functional PNKP deficiency and dysregulation of CycA/CDK1 mitotic activity during ZIKV infection of neural progenitors result in MC, contributing to the molecular mechanism underlying neurodevelopmental pathologies of congenital ZIKV infections." (PMID 35412344, 2022). "Here, we show that ZIKV infection caused the activation of cytoplasmic CycA/CDK1 and unscheduled mitotic entry in the presence of DNA breaks, which accumulated in infected cells due to the cytoplasmic localization of PNKP, leading to grossly abnormal mitoses culminating in MC." (PMID 35412344, 2022). "Here, we show that ZIKV infection induced activation of cytoplasmic CycA/CDK1, triggering unscheduled mitotic entry even in the presence of DNA damage, thus leading to MC." (PMID 35412344, 2022). "Our results indicate that ZIKV induces unscheduled activation of cytoplasmic CycA/CDK1 activity, activation that continuously increases until 21–24 h post ZIKV infection." (PMID 35412344, 2022). "The unscheduled activation of CycA/CDK1 in the presence of DNA damage in ZIKV infection suggested dysfunctional checkpoint signaling." (PMID 35412344, 2022). "We thus asked whether the abnormal accumulation of CycA and CDK1 during ZIKV infection resulted in active CDK1 complexes at the sites of RF assembly." (PMID 35412344, 2022). "Our results thus indicate that ZIKV infection induces cytoplasmic accumulation of CycA and CDK1." (PMID 35412344, 2022). "ZIKV infection also induced cytoplasmic accumulation and activation of CycA/CDK1 complexes." (PMID 35412344, 2022). "ZIKV infection induced MC and abnormal cytoplasmic accumulation of CDK1." (PMID 35412344, 2022).
cancer (769 papers, 2006 to 2026). A tumor composed of atypical neoplastic, often pleomorphic cells that invade other tissues. "The affected proliferation of cancer cells was associated with the down‐regulated cell cycle proteins, Cyclin B1 and CDK1." (PMID 40635123, 2025). "A study demonstrated that in cancer cells, Cdk2 can compensate for the loss of Cdk1 during mitotic entry when Cdk1 is rapidly degraded using the auxin-degron system." (PMID 40037894, 2025). "Numerous studies have demonstrated the upregulation of CDK1 in various cancers, where its dysregulation is closely linked to tumor development and progression." (PMID 40308776, 2025). "Dysregulation of CDK1 is frequently linked to uncontrolled cell proliferation and tumor development, positioning it as a vital player in cancer biology." (PMID 41278293, 2025). "Numerous cancer types are linked to CDK1 activation, and CDK1 phosphorylation across different substrates significantly hinders their roles in tumor formation." (PMID 39991589, 2025). "The suppression of CDK1 activity at this checkpoint is vital to blocking uncontrolled cellular proliferation, which is a hallmark of cancer progression." (PMID 41009727, 2025). "Recent research has demonstrated that CDK1 is over expressed in cancer and is intimately associated with unfavorable outcomes in LUAD." (PMID 40181976, 2025). "Overall, these findings demonstrate the critical role of HSP90 in supporting cancer cell survival through its cell cycle-associated client proteins, particularly CDK1." (PMID 40282517, 2025). "Increased ability to invade is also another hallmark of cancer potentially controlled by CDK1 by modulating several members of the Hippo pathway, thereby regulating neoplastic transformation, EMT and cell migration and invasion." (PMID 39800748, 2025). "CDK1 is reported to exhibit high oncogenic potential when aberrantly expressed and is associated with several cancers, including melanoma and lung cancer." (PMID 41357898, 2025). "In our study, four glycolysis genes (ENO1, STMN1, PKM, and CDK1) have been previously reported to be associated with cancer progression and drug resistance." (PMID 38840205, 2024). "CDK1, a key regulatory enzyme that controls cell cycle transition, is known to be associated with cancer proliferation and rapid tumor growth." (PMID 39171503, 2024). "Increased levels of CDK1 expression are linked to more advanced tumor grades and stages, suggesting its role in promoting cancer aggressiveness." (PMID 38895552, 2024). "High expression of CDK1 and Cyclin B1 and low levels of p21/p27 are frequently detected in various types of cancer and associated with cancer development and poor prognosis." (PMID 38789954, 2024). "Dysregulation of CDK1 expression is associated with the development of various malignant tumors and affects the survival probabilities of patients with different tumor types." (PMID 39464635, 2024). "As recent reports, CDK1 dysregulation is linked to carcinogenesis in many types of cancer, such as HCC associated with chronic HBV infection." (PMID 38895552, 2024). "We identified several proteins with high interaction scores (Cna2, Kif20a, Kif11, Cdk1, and Cdc20) that are closely associated with various cancers." (PMID 39596644, 2024). "It was reported that SRC phosphorylates CDK1 at Tyr15 and then cause mitotic slippage, leading to resistance of cancer cells to microtubule‐targeting agents." (PMID 37842807, 2024). "CDK1 (Cyclin-Dependent Kinase 1) is a critical regulator of the cell cycle, and its dysregulation has been implicated in various cancers." (PMID 38067357, 2023). "CDC25B is rendered inactive by LGH00031, which then dephosphorylates CDK1’s tyrosine to stimulate the CDK1/cyclin B complex, causing the cell cycle to be arrested and the proliferation of cancer cells to be inhibited." (PMID 37920248, 2023). "Collectively, AT7519 is also another promising CDK1-associated inhibitor for cancer treatment in the clinic." (PMID 37311884, 2023).
cancer (continued). "Increased CDK1 activity has been linked to an increased ability for cancer cells to invade and migrate." (PMID 37569750, 2023). "As a result, increased CDK1 expression has been linked to the progression of several cancers, including PCa and breast cancer." (PMID 36937454, 2023). "All these results suggested that dinaciclib is a promising CDK1-associated inhibitor for clinical treatment of cancer." (PMID 37311884, 2023). "For example, CDK1 expression is positively and highly associated with advanced cancer stages in lung and endometrial cancer." (PMID 36839989, 2023). "Increased expression of CDK1 in cancer patients is connected with higher risk of recurrence, and it is a promising prognostic marker for LUAD." (PMID 38071755, 2023). "To validate the potential regulatory function of NQO1 in cell cycle progression at the G2/M phase in cancer cells, we determined the protein levels of associated cyclin B1 and CDK1." (PMID 36793872, 2023). "The CDK1 (cyclin-dependent kinase 1) encodes a key regulator of the cell cycle that plays an important role in the development and progression of various types of cancer, including GC." (PMID 38069284, 2023). "These clinical studies will provide more information for the combination of CDK1 associated inhibitors with other anti-cancer agents for cancer treatment." (PMID 37311884, 2023). "Despite the expected inhibitory effect on CDK1 activity, the phosphorylation of Tyr15 has been found to be increased in several cancer types and has been associated with the development of drug resistance." (PMID 37898722, 2023). "Interaction of NOSTRIN with Cdk1 is associated with increased inhibitory Cdk phosphorylation thereby restricting cancer cell proliferation." (PMID 35642021, 2022). "We determined the association between CDK1 expression and prognosis of cancer patients using the Pronoscan database." (PMID 36090896, 2022). "CDK1 has been reported as a poor prognostic marker of LUAD that is highly correlated with the risk of cancer recurrence and poor overall survival in LUAD patients." (PMID 35885905, 2022). "It has been known that CDK1 was upregulated in several cancers and associated with the prognosis and progression." (PMID 35601741, 2022). "Lastly, it has been related to the HAT p300 inhibition and to a reduction in CDK1 transcription, which probably underlies the G2/M arrest observed in cancer cells." (PMID 35885908, 2022). "The present study aims to use pan-cancer analysis to investigate the relationship, similarities, and differences in genetic and cellular changes associated with CDK1 in various tumors and tumor microenvironments." (PMID 35681641, 2022). "Many researchers have found that CDK1 was tightly associated with the occurrence and development of several cancers." (PMID 35601741, 2022). "In conclusion, these analyses consistently showed that the CDK1 gene is significantly associated with the prognosis of patients with different cancer types and can significantly influence the survival of patients with these tumors." (PMID 36090896, 2022). "Pan-cancer analysis of genetic and epigenetic characteristics of CDK1 gene revealed differential mutations of CDK1 in different TCGA tumors." (PMID 36090896, 2022). "Bioinformatic analysis and immunohistochemical experiments confirmed that CDK1 is significantly upregulated in most common cancers and is strongly associated with prognosis." (PMID 36090896, 2022). "Effects of hepcidin downregulation are explained, specifically, increased cancer proliferation via activation of CDK1/STAT3 pathway and increased HCC risk due to reduction in a hepcidin-mediated protective effect against hepatic stellate cell activation." (PMID 35264787, 2022). "In particular, accumulation of cytoplasmic CDK1 is associated with cancer growth and survival rate in epithelial ovarian cancer." (PMID 34023852, 2021).
cancer (continued). "Upregulation of TTK, NEK2, and CDK1 was associated with growth factor-initiated signaling, i.e., salvage pyrimidine and purine pathways are frequently deregulated in cancer." (PMID 34072728, 2021). "CDK-1 has been implicated in several cancers, including ovarian, thyroid, bladder, colorectum, breast, and liver cancer." (PMID 33732631, 2021). "Among cell cycle-related proteins, CDK1 acts as an oncogene in cancers and is most associated with VIRMA in different breast cells." (PMID 33731118, 2021). "Loss of p21CIP1 unleashes CDK1 activity which causes W-CIN in otherwise chromosomally stable cancer cells." (PMID 33168930, 2021). "We performed a subgroup analysis on CIS‐accompanying cases and observed a significant association between high co‐expression of p‐TFCP2L1 and CDK1 in the main tumor and frequent cancer‐specific death (P = 0.015)." (PMID 31709755, 2020). "CDK1 over-activation frequently observed in cancers has the potential to cause aberrant BRD4 hyperphosphorylation persisting outside of mitosis to strengthen its target gene binding and confer BETi resistance." (PMID 32575711, 2020). "miR-16 was likely to suppress cancer growth by regulating the expression of genes such as CDK1 and CDK2, which are associated with cell cycle control and cellular proliferation." (PMID 32774515, 2020). "Dinaciclib was shown to drastically enhance EV-T killing effects on cancer lines that express good levels of death receptor (DR) 5, which are associated with suppression of CDK1, CDK9 and anti-apoptotic proteins." (PMID 32375399, 2020). "Over the past decade, a large number of researches have shown that dysregulation of CDK1 not only causes rapid tumor growth, but also leads to the spontaneous proliferation of cancer cells." (PMID 32127012, 2020). "Mechanistically, UA62784 preferentially activates CDK1 and induces cell cycle arrest and apoptosis in cancer cells with deficient SMAD4." (PMID 31569425, 2019). "CDK1 is a major mitotic regulating kinase involved in the G2/M phase of the cell cycle, and is upregulated in several cancers and also associated with clinicopathological factors." (PMID 31108958, 2019). "MK-1775, a first-in-class small-molecule inhibitor of WEE1 with undergoing clinical evaluation, abated phosphorylation of CDK1 at Tyr15 and caused mitotic catastrophe in cancer cells." (PMID 30323762, 2018). "CDK1 is a member of Cyclin-dependent kinases (CDKs) family, which are serine/threonine kinases whose deregulation is associated with cancer progression." (PMID 29568567, 2018). "This study included patients with stage UICC II, III, and IV, and the prognostic role of Cdk1 in cancer-related 5-year survival risk was only observed in stage II but not in the other stages or when all stages were combined." (PMID 25511643, 2014). "Among the 16 candidate cancer genes that encoded transcription factors, 13 were known to be tumorigenic and three were novel: CDK1, SNRPF, and ILF2." (PMID 23799036, 2013). "CCNB1 encoding cyclin B1 and CDK1 encoding cdc2 were overexpressed, as in many cancer types, both essential components of the cell cycle regulatory machinery." (PMID 19662092, 2009). "CCNB1, another key component in cell cycle control, has a role in G2/M progression, acting with CDK1 to control chromosome condensation; it has been implicated in tumourigenesis and in metastasis in different cancers." (PMID 19753302, 2009). "Overall, KY19382 and KY19334 could be used as agents to treat cSCC and other types of cancer caused by CDK1 overexpression, as well as diseases caused by cytoplasmic accumulation of CXXC5." (PMID 40887499, 2025).
cancer (continued). "However, although there have been some articles related to the study of CDK1 in CC and OC, there is still a deficiency of in-depth discussion regarding the role of CDK1 as a co-expressed gene in the clinical prognosis of the two cancers." (PMID 39991589, 2025). "CDK1 is a key regulator of the cell cycle, and its dysfunction is associated with various cancers." (PMID 40746357, 2025). "Aberrant activity of cell cycle kinases, including aurora kinase B (AURKB) and cyclin-dependent kinase 1 (CDK1), might lead to disrupted mitotic checkpoints, causing aneuploidies and uncontrolled proliferation, which are critical hallmarks of cancers." (PMID 41357898, 2025). "Blocking CDK1 may cause tumor cells to stop dividing and undergo a programmed cell death pathway, making it a potential target for cancer treatment." (PMID 38895552, 2024). "Furthermore, several clinical trials of CDK1 associated inhibitors combining with other anti-cancer agents are ongoing to evaluate the combination treatment in cancer (NCT03579836; NCT03484520; NCT01434316; NCT01676753)." (PMID 37311884, 2023). "Multi-dimensional bioinformatics analysis from The Cancer Genome Atlas (TCGA) and Gene Expression Omnibus (GEO) datasets confirmed that CDK1 was significantly overexpressed in cancer cells and strongly associated with prognosis in many types of cancer, including OC." (PMID 37569750, 2023). "To further explore the involvement of the DDR proteins in the NORAD-mediated accumulation of γH2Ax we used siRNAs to KD two of the hits identified in the NORAD-associated proteome (LC-MS/MS experiment), namely PARP1 and CDK1, both proteins being extensively linked to cancer and DXR response." (PMID 37680988, 2023). "Particularly aberrant Cdk1 activation at the G2/M checkpoint by kinase inhibitors causing unscheduled mitotic entry and mitotic arrest was found to lead to DNA damage and cell death selectively in cancer cells." (PMID 38020882, 2023). "Finally, alteration of CDK1 expression level has been widely associated to cancer progression, as already extensively reviewed." (PMID 37898722, 2023). "Deregulation of CDK1 has been closely associated with cancer." (PMID 37898722, 2023). "Cdk1 activity is inhibited by phosphorylation induced by Myelin transcription factor 1 (MYT1) and by the reduced expression of Cdk1 phosphatase called cell division cycle 25C (cdc25), which is highly expressed in cancer and is associated with tumor development." (PMID 37838167, 2023). "Finally, we describe how deregulation of CDK1 expression and activation has been closely associated with cancer progression and drug resistance." (PMID 37898722, 2023). "The combined CDK1 associated inhibitors with other anticancer agents might improve the chemotherapeutic benefits and improve clinical outcome in cancer development." (PMID 37311884, 2023). "As early as 2007, it was discovered that sustained activation of CDK1 causes cells to fail to exit mitosis normally, resulting in the appearance of abnormal cells that have been shown to be associated with the development of cancer." (PMID 36004205, 2022). "Up-regulation of CDK1 genes may be indicative of poor survival rates and a higher risk for cancer recurrence." (PMID 35632527, 2022). "In addition, mutations that influence the status of CDK1 in cancer cells will be determined for the application of USP7 inhibitors in the clinic." (PMID 34445496, 2021). "These properties of CDK1 suggest that in the opposite scenario, overexpression of the protein could result in replication of cells with faulty DNA, causing cancer cell proliferation." (PMID 34503199, 2021).